MIR4718 (microRNA 4718)
Synonyms: hsa-mir-4718
Gene: MicroRNA gene on chromosome 16 (12,720,321 to 12,720,371, forward strand). Ensembl gene ENSG00000264733.
Homologues: Orthologues: chimpanzee MIR4718 (100% identical).
Diseases named in the same sentence as MIR4718 in open-access papers:
MIR4718 is named in the same sentence as 1 disease in open-access papers, as found by Europe PMC text mining. Sharing a sentence is not in itself a finding about the gene and the disease.
MIR4718 shares sentences with these, for which no sentence is quoted: microcephaly (1 paper).